SNORD102 (small nucleolar RNA, C/D box 102)
Synonyms: U102; RNU102; Z18
Gene: Small nucleolar RNA gene on chromosome 13 (27,255,064 to 27,255,135, forward strand). Ensembl gene ENSG00000207500.
Gene Ontology:
Biological process: RNA processing
Cellular component: nucleolus
Homologues: Orthologues: macaque SNORD102 (97% identical), rabbit SNORD102 (94% identical), guinea pig SNORD102 (90% identical), mouse Gm25091 (88% identical), rat Snord102 (88% identical), pig SNORD102 (86% identical).
Diseases named in the same sentence as SNORD102 in open-access papers:
SNORD102 is named in the same sentence as 1 disease in open-access papers, as found by Europe PMC text mining. Sharing a sentence is not in itself a finding about the gene and the disease.
SNORD102 shares sentences with these, for which no sentence is quoted: cancer (1 paper).